HOXA4 (homeobox A4)
Diseases named in the same sentence as HOXA4 in open-access papers (continued):
Sharing a sentence is not in itself a finding about the gene and the disease.
chronic lymphocytic leukaemia (2 papers, 2019 to 2022). "Hypermethylation of the promoter-located CpG island usually leads to transcriptional inhibition and is involved in the inactivation of many tumor suppressor genes, such as HOXA4 in chronic lymphocytic leukemia (CLL)." (PMID 31013831, 2019).
chronic lymphoid leukemia (2 papers, 2013 to 2021). "Apart from AML, another study had demonstrated the contribution of HOXA4 promoter hypermethylation in chronic lymphoid leukemia (CLL)." (PMID 23484077, 2013).
colon cancer (2 papers, 2023 to 2025). "HOXA4 overexpression promoted self-renewal and overpopulation of colon cancer stem cells." (PMID 37334354, 2023).
lung adenocarcinoma (2 papers, 2019 to 2022). A carcinoma that arises from the lung and is characterized by the presence of malignant glandular epithelial cells. "Therefore, our evaluation also supports the role of HOXA4 as a potential tumor suppressor in lung adenocarcinoma." (PMID 31503425, 2019).
non-small cell lung carcinoma (2 papers, 2022 to 2024). A group of at least three distinct histological types of lung cancer, including non-small cell squamous cell carcinoma, adenocarcinoma, and large cell carcinoma. "The association of HOXA-AS2, HOXA11,HOTTIP, HOXA1, HOXA3 and HOXA4 expression with survival of non-small-cell lung cancer." (PMID 39121297, 2024). "There have been several studies that reported the expression pattern of HOXA4 and HOXA5 in non-small cell lung cancer as well as the influence of HOXA4 and HOXA5 in biological behaviors of non-small cell lung cancer cells 10-13." (PMID 35370463, 2022).
aneurysm (1 paper, 2011). Bulging or ballooning in an area of an artery secondary to arterial wall weakening. "It is, therefore, plausible that loss of HOXA4 function in medial SMCs contributes to adverse phenotypic changes in aneurysms, including disruption of cell-cell interactions." (PMID 21627813, 2011).
asthma (1 paper, 2023). "Furthermore, DNAm markers in HOXA7 and HOXA4 genes have been associated with lung development and asthma, while DNAm in AURKC has been associated with lung function in Latino children with asthma." (PMID 36979655, 2023).
brachyolmia (1 paper, 2023). Brachyolmia is a rare, clinically and genetically heterogeneous group of bone disorders characterized by short trunk, mild short stature, scoliosis and generalized platyspondyly without significant abnormalities in the long bones. "Finally, the rib and spine phenotypes associated with brachyolmia and metatropic dysplasia could be contributed to the altered expression of HOXA4 to HOXA7 as it has been shown that these genes are associated with rib and spine patterning, and alterations in expression have led to defects." (PMID 36810131, 2023).
brain cancer (1 paper, 2020). A primary or metastatic malignant neoplasm affecting the brain. "Notably, there were 6 HOX genes, namely HOXA2, HOXA4, HOXB2, HOXB3, HOXB4, and HOXC4, which changed expression only in brain cancer (either in GBM, brain lower grade glioma (LGG), or in both)." (PMID 32545894, 2020).
campomelic dysplasia (1 paper, 2013). "Hoxa4 may have a role in vertebral development in mice, while mutations in the human SOX9 gene have been found to cause campomelic dysplasia, a disease characterised by shortness and bowing of long tubular bones, hypoplastic scapulae and narrow iliac wings." (PMID 24176111, 2013).
chordoma (1 paper, 2023). Chordomas are rare malignant tumors arising from embryonic remnants of the notochord in axial skeleton. "Chordoma-specific DMRs were also found in location of homeobox domain genes (e.g. DMRs in HOXA4, HOXA5, HOXD3, HOXD4 MNX1, and NFIX) especially on chromosome 2 at HOXD cluster." (PMID 37434245, 2023).
cognitive decline (1 paper, 2021). "The decreased levels of methylation for probes in the DMR annotated to HOXA4 were associated with faster rate of cognitive decline; in contrast, hypermethylation was reported for probes annotated to the HOXA gene cluster in the brain in patients with AD." (PMID 34654479, 2021). "In blood, the increased levels of methylation or probes in the DMR annotated to HOXA4 were associated with slower rate of cognitive decline." (PMID 34654479, 2021).
endometrial cancer (1 paper, 2019). Primary or metastatic malignant neoplasm involving the endometrium (mucous membrane that lines the endometrial cavity). "Also, poor prognosis of patients with endometrial cancer is associated with higher levels of HOXA4, HOX5, HOXA6, HOXA7, and HOXB9 expression, whereas favorable prognosis of patients with endometrial cancer is associated with higher levels of HOXB5 and HOXB6 expression." (PMID 30866492, 2019).
growth disorders (1 paper, 2017). "We hypothesize that HOXA4 plays a role in growth-regulating pathways affecting SRS, related growth disorders, and also stature in general." (PMID 29146936, 2017).
megacolon (1 paper, 2011). "Conversely, transgenic mice overexpressing the Hoxa4 gene develop congenital megacolon due to abnormalities in the enteric nervous system." (PMID 21627813, 2011).
mesothelioma (1 paper, 2014). A usually malignant and aggressive neoplasm of the mesothelium which is often associated with exposure to asbestos. "Mesothelioma cells express high levels of two HOX genes, HOXA4 and HOXA5; when HXR9 is added to block HOX activity, mesothelioma cells but not normal mesothelial cells undergo apoptosis." (PMID 25525461, 2014).
metastasis (1 paper, 2018). The spread or migration of cancer cells from one part of the body (where they first appeared) to another. "HOXA4 expression was associated with tumor size, TNM stage, lymph node metastasis and prognosis." (PMID 29700285, 2018).
oral cancer (1 paper, 2012). "In healthy oral mucosa derived from patients without risk factors for oral cancer, only HOXA1, HOXA2 and HOXA4 were expressed, whereas the abundance of transcripts in histologically normal-looking oral mucosa near OSCC and in OSCC samples was higher." (PMID 22498108, 2012).
prostate carcinoma (1 paper, 2009). A carcinoma that arises from epithelial cells of the prostate gland. "Some of these genes have known functions in prostate cancer, such as FGFR1, BCL2, HOXC5, HOXA4, TWIST1, EZH2, KLF4, CTGF." (PMID 19262738, 2009).
tumor (22 papers, 2011 to 2025). "Tumor purity was negatively associated with the expression of HOXA4 and HOXA5 in LUAD (P<0.05)." (PMID 35370463, 2022). "Taken together these findings suggest that HOXA4 is indeed primarily a suppressor of invasion, and it is possible then that the increased HOXA4 expression observed in invasive cell lines may be linked to a tumour-suppressive response." (PMID 21906307, 2011). "HOXA4 expression is inversely related to cell cycle, metastasis, and Wnt signaling pathway, and its overexpression can inhibit tumor cell proliferation, migration and invasion." (PMID 32019071, 2020). "At 33 days after inoculation, tumor size, and weight was noticeably decreased in the HOXA4 overexpression group compared with the vector group." (PMID 29700285, 2018). "We found that HOXA4 mRNA expression was lower in tumor tissues (n = 100) than in normal lung tissues (n = 40) (2.01 ± 0.06 vs. 3.49 ± 0.21, P < 0.0001)." (PMID 29700285, 2018). "Western blotting analysis revealed that tumor tissues formed from HOXA4-overexpressing cells displayed higher levels of HOXA4 and GSK3β and lower levels of β-catenin than did cells in the vector group." (PMID 29700285, 2018). "We found that the tumor growth in the HOXA4 overexpression group was significantly slower than that in the vector group." (PMID 29700285, 2018). "Additionally, the expression of tumor-associated genes such as CT45A3, TPBG, HOXA4, ZNF185, and SNX19 was significantly downregulated." (PMID 40136427, 2025). "Previous reports have shown that HOXA4 acts as a tumor suppressor in various cancers." (PMID 37898994, 2024). "Analysis of bulk expression data from both tumor cohorts identified high variance in expression levels of several H3K27me3-associated genes in both PFAs and H3K27M DMGs with greatest variability in homeobox genes including HOXA2, HOXA4, and LHX2.." (PMID 36759899, 2023). "HOXA4 or HOXA5 may serve as tumor-suppressors in the occurrence and development of LUAD by acting on immune cells or affecting the proliferation, migration and invasion of LUAD cells." (PMID 35370463, 2022). "However, examples of suppressive influences on tumor progression also exist, for example by HOXA5 in the maintenance of the epithelial phenotype, and HOXA4 in the inhibition of tumor cell migration [170*]." (PMID 31636382, 2020). "HOXA4 has also been reported to be a potential tumor suppressive gene." (PMID 29876008, 2018). "Overexpression of HOXA4 in xenograft tumors also decreased tumor growth and Wnt signaling." (PMID 29700285, 2018). "Analysis of HOX genes that are known to have oncogenic or tumor suppressive functions likewise reveals considerable variation, although Met-5A showed higher expression of the potential tumor suppressor genes HOXA4 and HOXA5 compared to the malignant cell lines." (PMID 26867567, 2016). "The HOXA4, CYP4F12, and ADM2 were positively correlated with the immune and stromal score but negatively correlated with tumor purity." (PMID 37955724, 2023). "The expression of HOXA4 and HOXA5 in LUAD were negatively correlated with tumor purity and positively correlated with the infiltration of various immune cells such as B cells, T cells and macrophages." (PMID 35370463, 2022). "For instance, in LSCC we observed four TFs (HOXA4, HOXA5, TAL1, ZNF132) undergoing promoter hypermethylation in at least 50 % of the LSCC tumour samples where these TFs were underexpressed." (PMID 27562343, 2016). "Meanwhile, tumor suppressors HIPK2, HOXA4, and MLL3 were predicted to be similarly targeted by miR-934." (PMID 26472042, 2015). "The Auersperg team found that HOXA4 expression was increased in invasive compared to noninvasive tumours, although it was acting as a tumour suppressor by reducing cell migration." (PMID 31382546, 2019).
tumor (continued). "Inhibition of miR-30a induced significant upregulation of BNIP3L, PRDM9, and SEPT7, while inhibition of miR-934 increased the expression of HIPK2, HOXA4, and MLL3, suggesting that the miRNAs exert negative regulatory effects on these established tumor suppressors." (PMID 26472042, 2015).
cancer (18 papers, 2015 to 2025). A tumor composed of atypical neoplastic, often pleomorphic cells that invade other tissues. "Homeobox genes are abnormally expressed in cancer cells and changes in the expression of HOXA4 has been specifically associated with colorectal, ovarian and lung cancer." (PMID 40180905, 2025). "HOXA-AS2 is a 1048-bp lncRNA located between the HOXA3 and HOXA4 genes in the HOXA cluster that is tightly associated with inflammation-linked cancers." (PMID 34511122, 2021). "In fact, whole‐genome sequencing of young patients with non‐small‐cell lung cancer detects mutations of HOXA4 as well as those of MST1, the upstream kinase of the Hippo signaling pathway, as cancer‐associated gene mutations." (PMID 32147946, 2020). "Similarly, the role of HOXA4 gene expression during carcinogenesis, prognosis, and drug resistance is also different among cancers." (PMID 33816499, 2021). "Genes involved in angiogenesis (HOXA2, HOXC5), genome instability (HOXC5, HOXC11), deregulating cellular energetics (HOXA4, HOXC5), and metastasis (HOXA2) were all up-regulated in ecDNA(+) cancers." (PMID 38896472, 2024). "There have been literature documents of the involvements of HOXA4 and HOXA5 in formation and progression of various human cancers through active or inhibitory roles in proliferation, growth, migration and apoptosis in cancer cells 37-42." (PMID 35370463, 2022). "The differential expression of HOXA4 and HOXA5 in LUAD also showed preferable ability of discriminating LUAD from non-cancer lung samples." (PMID 35370463, 2022). "In our models, Napabucasin treatment similarly reduced the stemness property of lung colonizing cancer cells, illustrated by a significant decrease in the expression of stemness genes, e.g. CK14, SOX5, SOX9, and HOXA4, and an increased expression of the differentiated cell marker, CK18." (PMID 31086186, 2019).
HOXA4 also shares sentences with these, for which no sentence is quoted: colorectal cancer (3 papers); chronic myeloid leukaemia (2); gastric cancer (2); neuroblastoma (2); acute monocytic leukemia (1); Alzheimer disease (1); anaemia (1); anencephaly (1); astrocytoma (1); cardiovascular diseases (1); cervical cancer (1); head and neck squamous cell carcinoma (1); insulinoma (1); ischemia (1); lymph node metastasis (1); lymphoma (1); multiple myeloma (1); oligodendroglioma (1); pancreatic cancer (1); periodontitis (1); psychiatric disorder (1); renal clear cell carcinoma (1); Silver-Russell syndrome (1).